GPR15 (G protein-coupled receptor 15)
Description:
G protein-coupled receptor that plays an important role in immune homeostasis. Acts via its natural ligand GPR15LG, a chemokine-like polypeptide strongly expressed in gastrointestinal tissues. GPR15-GPR15LG signaling axis regulates intestinal homeostasis and inflammation through the migration of immune cells. Controls thereby the specific homing of T-cells, particularly FOXP3+ regulatory T-cells (Tregs), to the large intestine lamina propria (By similarity). Also required for skin localization of thymus-derived dendritic epidermal T-cells (By similarity). Plays an important role in mediating cytoprotective function as well as angiogenesis of thrombomodulin (By similarity). Mechanistically, preferentially signals through the Gi/o pathway to inhibit adenylate cyclase activity and activate a phosphatidylinositol-calcium second messenger system that regulates the release of Ca(2+) ions from intracellular stores. (Microbial infection) Acts as an alternative coreceptor with CD4 for HIV-1 infection.
Synonyms: BoB
Tractability: Small molecule: it belongs to a druggable protein family. Antibody: UniProt places it where antibodies can reach, with high confidence; its Gene Ontology location is reachable by antibodies, with high confidence; UniProt predicts a signal peptide or a membrane-spanning region.
Target class: Family A G protein-coupled receptor; Membrane receptor
Gene: Protein-coding gene on chromosome 3 (98,531,978 to 98,534,681, forward strand). Ensembl gene ENSG00000154165.
Subcellular location: Cell membrane
Pathways (Reactome):
Signal Transduction: G alpha (s) signalling events
Gene Ontology:
Molecular function: coreceptor activity; G protein-coupled receptor activity; protein binding; virus receptor activity
Biological process: angiogenesis; G protein-coupled receptor signaling pathway; symbiont entry into host cell; T cell migration
Cellular component: cytoplasm; endosome; plasma membrane; membrane
Genetic constraint (gnomAD): Loss-of-function variants: 17 observed, 20.9 expected, observed/expected ratio (o/e) 0.81, 90% interval 0.56 to 1.22. The upper end of that interval is the gene's LOEUF score, 1.22, which puts it in group 5 of 6, group 1 being the genes least tolerant of losing a copy. Missense variants: 458 observed, 453.26 expected, observed/expected ratio (o/e) 1.01, 90% interval 0.94 to 1.09. Synonymous variants: 170 observed, 182.03 expected, observed/expected ratio (o/e) 0.93, 90% interval 0.82 to 1.06.
Homologues: Orthologues: chimpanzee GPR15 (100% identical), macaque GPR15 (97% identical), rabbit GPR15 (86% identical), pig GPR15 (85% identical), guinea pig GPR15 (84% identical), dog GPR15 (81% identical), rat Gpr15 (77% identical), mouse Gpr15 (76% identical). Paralogues in human: GPR25 (31% identical), APLNR (27% identical), AGTR1 (26% identical), AGTR2 (23% identical), BDKRB1 (22% identical), BDKRB2 (21% identical), RXFP4 (20% identical).
Diseases named in the same sentence as GPR15 in open-access papers:
GPR15 is named in the same sentence as 70 diseases in open-access papers, as found by Europe PMC text mining. Sharing a sentence is not in itself a finding about the gene and the disease. The quoted sentences say what the papers report.
colitis (13 papers, 2015 to 2025). Inflammation of the colon. "Specifically, prolonged exposure to cigarette smoke has contrasting, model-dependent effects on colitis severity, whereby upregulation of Gpr15 expression is associated with exacerbated disease in the TNBS model but mitigated disease in the DSS model." (PMID 40957881, 2025). "Cigarette smoke exposure followed by TNBS-induced colitis led to reduced weight loss and diminished clinical scores, colon length, and less severe pathological and endoscopic findings in Gpr15−/− mice than in Gpr15+/+ mice." (PMID 40957881, 2025). "Conversely, Gpr15 deficiency in the DSS-induced colitis group under the same conditions significantly reduced the correlation with Foxp3 and Treg cells." (PMID 40957881, 2025). "Collectively, these results highlight a strong association between Gpr15 expression and colitis activity." (PMID 40957881, 2025). "In the AOM/DSS colitis-associated colon cancer model, we observed increased colonic polyps and lower survival in Gpr15+-KO compared to Gpr15-Het mice." (PMID 38074634, 2023). "Our results thus indicate that GPR15 loss led to increased tumor burden, severe disease pathology and poor survival in the AOM-DSS CAC disease model alludes to a protective role of GPR15 in colitis associated colon cancer development." (PMID 38074634, 2023). "Cigarette smoke exposure followed by DSS-induced colitis resulted in significantly greater weight loss, higher clinical scores, shorter colon lengths, and more severe pathological and endoscopic assessments in Gpr15−/− mice than in Gpr15+/+ mice." (PMID 40957881, 2025). "However, the incomplete loss or reversal of the effects of cigarette smoke in mice with Gpr15 deficiency demonstrates that colitis severity is modulated by both Gpr15-dependent and Gpr15-independent mechanisms." (PMID 40957881, 2025). "Consequently, two weeks of dietary L-Trp supplementation nearly double the colonic GPR15+ Treg cells via GPR15-mediated homing and substantially reduce the future risk of colitis." (PMID 37963876, 2023). "First, we discovered that only two weeks of dietary L-Trp supplementation was sufficient to increase the number of colonic GPR15+ Treg cells and reduce the future risk of experimental colitis, which demonstrates how influential dietary L-Trp is on colonic T cell responses." (PMID 37963876, 2023). "In addition to colitis, GPR15 has also been implicated in the pathogenesis of CRC." (PMID 37457732, 2023). "IL-17A production and Th17 cell accumulation were significantly lower in the colons of Gpr15−/− mice than in those of Gpr15+/+ mice with TNBS-induced colitis." (PMID 40957881, 2025). "Th17 cells isolated from cigarette smoke-treated Gpr15+/+ and Gpr15−/− mice were transferred into Gpr15−/− mice with TNBS-induced colitis." (PMID 40957881, 2025). "In combination with DSS-induced colitis, Gpr15−/− mice presented a greater reduction in the percentage of Treg cells than did Gpr15+/+ mice." (PMID 40957881, 2025). "Building upon these findings, further mechanistic investigations highlight the context-dependent immunomodulatory role of GPR15 in shaping T-cell responses in models of colitis following cigarette smoke exposure." (PMID 40957881, 2025). "Surprisingly, Tgfb1, Il17ra, Il23a, Il6ra, Ror1, Tnf, Tgfbr2, Ccr2, and Il17c were downregulated by cigarette smoke exposure in TNBS-induced colitis Gpr15−/− mice compared with similarly treated Gpr15+/+ mice." (PMID 40957881, 2025). "Mechanistic evidence specifically indicates that, in the TNBS-induced colitis model, GPR15 promotes STAT3-dependent Th17 activation and IL-17-mediated pathology." (PMID 40957881, 2025). "These reductions were also observed in Gpr15−/− mice exposed to both cigarette smoke and TNBS-induced colitis compared with Gpr15+/+ mice." (PMID 40957881, 2025). "In TNBS-induced CD-like colitis, cigarette smoke exposure upregulates GPR15 expression on T cells, driving their differentiation into Th17 cells and exacerbating disease progression." (PMID 40957881, 2025).
colitis (continued). "In contrast, in DSS-induced UC-like colitis, cigarette smoke exposure similarly increases GPR15 expression on T cells but promotes their differentiation into Treg cells, conferring a protective effect against disease progression." (PMID 40957881, 2025). "Gpr15 deficiency significantly weakened the association between Il17c and immune cells, particularly Th17 cells, in the TNBS-induced colitis group following cigarette smoke exposure." (PMID 40957881, 2025). "Conversely, in the DSS model, extended smoke exposure alleviated colitis, while Gpr15 expression also increased, underscoring model-dependent effects." (PMID 40957881, 2025). "The Th17 signaling pathway was downregulated in TNBS-induced colitis Gpr15−/− mice following cigarette smoke exposure." (PMID 40957881, 2025). "GPR15, previously reported to direct regulatory T (Treg) cell colon homing, was upregulated in the colon tissues of both chemically induced colitis models after smoke exposure." (PMID 40957881, 2025). "In TNBS-induced CD-like colitis, cigarette smoke upregulates GPR15 on T cells, promoting Th17 differentiation and aggravating the disease." (PMID 40957881, 2025). "In contrast, in the DSS-induced colitis model, GPR15 activation enhances SMAD3/STAT5 signaling and promotes the differentiation of iTregs, thereby contributing to intestinal integrity." (PMID 40957881, 2025). "Heatmaps revealed that Th17-associated genes were significantly downregulated in the colonic tissue of TNBS-induced colitis Gpr15−/− mice after cigarette smoke exposure." (PMID 40957881, 2025). "Conversely, Treg cells from cigarette smoke-treated Gpr15+/+ and Gpr15−/− mice were transferred into Gpr15−/− mice with DSS-induced colitis to assess their protective effects." (PMID 40957881, 2025). "DSS-induced UC-like colitis similarly increases GPR15 but drives Treg differentiation, alleviating disease severity." (PMID 40957881, 2025). "We previously identified an important function of GPR15 in T cell traffic to the inflamed colon and colitis pathogenesis." (PMID 38074634, 2023). "In contrast to the well-studied role of GPR15 in colitis and other inflammation conditions, the function of GPR15-GPR15L signaling axis in CRC is poorly understood." (PMID 38074634, 2023). "The orphan GPCR GPR15 directs T cell homing to the developing epidermis and to the colon and regulates colitis." (PMID 28936214, 2017). "GPR15 mediates the colon localization of CD4+ CD25+ effector and regulatory cells to the colon and has been implicated in colitis in models of infectious and autoimmune intestinal inflammation." (PMID 28936214, 2017). "In aninfection‐induced colitis model, Gpr15 knockout micewere more prone to tissue damage and inflammatory cytokine expression." (PMID 26650439, 2015). "In DSS-induced colitis, flow cytometry revealed significantly fewer Treg cells among the mononuclear cells isolated from the PBMCs, MLNs, and LPMCs of Gpr15−/− mice compared with those of Gpr15+/+ mice." (PMID 40957881, 2025). "Additionally, these cytokine levels were elevated in Gpr15−/− mice exposed to cigarette smoke followed by DSS-induced colitis compared with those in Gpr15+/+ mice under the same conditions." (PMID 40957881, 2025). "Additionally, in Gpr15-deficient mice, cigarette smoke exposure reduced the severity of TNBS-induced colitis, whereas in DSS-induced Gpr15-deficient UC models, it re-resulted in more severe disease progression." (PMID 40957881, 2025). "Furthermore, the loss of Gpr15 has divergent effects on chemically induced colitis under cigarette smoke exposure, conferring protection in TNBS-induced colitis while aggravating disease in the DSS model." (PMID 40957881, 2025). "To explore the role of Gpr15 in Th17 cell regulation during TNBS-induced colitis following cigarette smoke exposure, we performed flow cytometric analysis of peripheral blood mononuclear cells (PBMCs), mesenteric lymph node cells (MLNs), and colonic lamina propria mononuclear cells (LPMCs)." (PMID 40957881, 2025).
colitis (continued). "Consistently, in Gpr15+/+ mice, prolonged cigarette smoke exposure in the TNBS model led to aggravated colitis, as reflected by greater weight loss, elevated DAI, colon shortening, and worsened histological and endoscopic scores, accompanied by increased Gpr15 expression." (PMID 40957881, 2025). "Collectively, these results indicate that the Tg(hGPR15) phenotype with elevated GPR15 levels could aggravate TNBS-induced colitis while offering better protection against DSS-induced ulcerative colitis under cigarette smoke exposure." (PMID 40957881, 2025). "Notably, Th17 cell accumulation was markedly lower in Gpr15−/− mice exposed to TNBS colitis and cigarette smoke than in Gpr15+/+ mice under the same conditions." (PMID 40957881, 2025). "Additionally, exposure to cigarette smoke and TNBS-induced colitis further elevated cytokine levels in Tg(hGPR15) mice compared with those in Gpr15+/+ mice." (PMID 40957881, 2025). "Similarly, in the DSS-induced colitis model, Gpr15−/− mice presented significantly lower Foxp3 expression in the colon than did Gpr15+/+ mice." (PMID 40957881, 2025). "Similarly, the TGF-beta signaling pathway was also suppressed in DSS-induced colitis Gpr15−/− mice under the same conditions." (PMID 40957881, 2025). "To examine the role of GPR15 in CRC development, we used the well-characterized AOM-DSS induced colitis-associated colon cancer (CAC) experimental model to study the course of tumor formation and development in Gpr15-sufficient (Het) and Gpr15-deficient (knockout; KO) mice." (PMID 38074634, 2023). "In sharp contrast, colitis in the anti-CD40 antibody model is aggravated in Gpr15−/− mice." (PMID 32922401, 2020). "This uncovered a complex, context-dependent role of GPR15 in colon inflammation: in support of a pivotal, disease-promoting role of GPR15 in colitis, GPR15 is required for T effector cell recruitment into the colon in the CD45RBhigh T cell transfer model of colitis." (PMID 32922401, 2020). "Notably, compared with Gpr15+/+ mice subjected to the same TNBS induction, Gpr15−/− mice presented alleviated symptoms of TNBS-induced colitis, including reduced body weight loss, a lower DAI, and colon shortening, as well as improved histopathology and colonoscopy scores." (PMID 40957881, 2025). "Studies from our group and others have identified GPR15 as a mucosal chemoattractant/trafficking receptor that facilitates migration of effector and regulatory T cells to sites of inflammation in the large intestine and plays a crucial role in colitis pathogenesis." (PMID 38074634, 2023). "To further investigate the effects of GPR15 overexpression on smoking-related colitis, we induced acute colitis via TNBS and DSS in transgenic C57BL/6JGpt-Tg (human GPR15) mice and their littermate controls." (PMID 40957881, 2025). "GPR15 regulates distinct immunological pathways under these conditions, including Th17 responses in TNBS-induced colitis and Treg responses in DSS-induced colitis." (PMID 40957881, 2025). "Compared with Gpr15+/+ mice, exposure to cigarette smoke followed by DSS-induced colitis further reduced the levels of these cytokines." (PMID 40957881, 2025). "The chemoattractant receptor, G protein-coupled receptor 15 (GPR15), promotes colon homing of T cells in health and colitis." (PMID 38074634, 2023). "Here the authors show that L-tryptophan promotes the development of GPR15+ Treg cells via the host IDO1/2 pathway and that tryptophan consumption in mice reduces severity of colitis in a C. rodentium mouse model." (PMID 37963876, 2023). "The Gpr15 gene knockout (KO) reduced Treg numbers in LILP and exacerbated colitis induced by Citrobacter rodentium infection." (PMID 37457732, 2023). "GPR15 has been shown to have its expression modulated by both gut microbiota and TGF-β, with knockout of this receptor giving rise to colitis, rescued by transfer of Tregs with intact GPR15, suggesting GPR15 has a crucial role to play in mucosal health." (PMID 38283365, 2023).
colitis (continued). "Moreover, GPR15 expression was previously reported to direct Treg cells to the large intestine and defects in GPR15 led to increased susceptibility to colitis in a Citrobacter rodentium infection model and reduced suppression or rescue of inflammation in anti-CD40 and T cell transfer colitis models." (PMID 34017333, 2021). "Inducible Treg-specific haploinsufficiency of Ptpn2 enhanced colitis-induced SKG arthritis and led to specific joint accumulation of GPR15+ exTregs." (PMID 33055428, 2020). "ELISAs revealed significantly lower IL-17 and IL-6 levels in Gpr15−/− mice with TNBS-induced colitis with or without smoke exposure." (PMID 40957881, 2025). "Additionally, the percentage of Treg cells remained unchanged in both Gpr15+/+ and Gpr15−/− mice subjected to smoke and TNBS-induced colitis." (PMID 40957881, 2025). "We observed that prior L-Trp supplementation significantly reduced the inflammation and pathology of colitis in WT mice, but not in Gpr15 KO mice both in C. rodentium-mediated colitis (and) and DSS colitis." (PMID 37963876, 2023). "utilized a humanized mouse model to comparatively determine the role of GPR15 and α4β7 integrin, in which human peripheral blood T cells from patients with UC were transferred into mice and examined for migration to the colon in dextran sulfate sodium (DSS)-induced colitis." (PMID 37457732, 2023). "Some independent studies have suggested that GPR15-expressing effector T cells (TE), rather than Treg cells, mediate local colonic inflammation, while another study showed increased GPR15 expression in peripheral blood Treg cells, but not in TE cells in patients with ulcerative colitis (UC)." (PMID 36551327, 2022). "Hence, GPR15 is capable of directing the colon homing of both Treg and Teff CD4+ T cells in mice, and the impact of this receptor in colitis pathology will depend on the experimental settings regarding the relative requirement of Treg and Teff subsets for the development of colitis." (PMID 37457732, 2023). "In addition, in a non-infectious colitis model in Rag2-/- mice, where CD40 stimulation induced innate immune cell-mediated colitis, adoptive transfer of Tregs from wild-type mice reduced colitis severity and tissue damage, but Tregs from Gpr15 KO mice failed to do so." (PMID 37457732, 2023).
colorectal cancer (7 papers, 2021 to 2025). A primary or metastatic malignant neoplasm that affects the colon or rectum. "GPR15+ Tregs may also be indirectly linked to AIRE deficiency as tumor associated GPR15+ Tregs in colorectal cancer has been shown to have a thymic origin." (PMID 34526996, 2021). "However, colorectal cancer in progressed stages could be additionally infiltrated by tumor-associated GPR15+ Tregs of the Th17-like phenotype." (PMID 34639163, 2021). "A recent study however, showed that GPR15 is upregulated in human colorectal cancer cells and that silencing of GPR15 inhibited the growth of colorectal cancer cells, using in vitro assays." (PMID 38074634, 2023). "Recently, it was demonstrated that patients with colorectal cancer have increased frequencies of GPR15+ Tregs in peripheral blood, correlating with high numbers of GPR15+ Tregs infiltrating the colonic cancerous lesions." (PMID 34526996, 2021). "Repression of GPR15 strongly induced apoptosis and inhibited colorectal cancer cell growth, migration, and invasion." (PMID 34639163, 2021). "In contrast, another recent report showed an upregulation of GPR15 in colorectal cancer in comparison to normal adjacent tissue." (PMID 34639163, 2021). "GPR15 promotes colorectal cancer by promoting the recruitment of Tregs." (PMID 40689396, 2025). "In colorectal cancer (CRC), GPR15 expression correlated negatively with the expression of microRNA (miRNA) miR-182-3-p, indicating potential inhibition of GPR15 expression by epigenetic mechanisms." (PMID 34639163, 2021). "Beyond the traditional chemotactic mediators, recent studies have also demonstrated that the G protein-coupled receptor 15 (GPR15), an unconventional chemokine receptor, directs the infiltration of Treg cells into the colon and subsequently promotes immune evasion of colorectal cancer." (PMID 36569832, 2022).